CDH1 (cadherin 1)
Diseases named in the same sentence as CDH1 in open-access papers (continued):
Sharing a sentence is not in itself a finding about the gene and the disease.
breast carcinoma (continued). "To investigate if the level of CDH1 (E-cadherin) gene expression in tumor samples from breast cancer patients is also associated with IBC, we compared the levels of CDH1 gene expression in tumor samples from IBC and non-IBC patients." (PMID 30023340, 2018). "Histologically, non-cohesive cancer cells are observed in ILC due to the loss of E-cadherin, either due to mutations inactivating the E-cadherin gene (CDH1), CDH1 haploisufficiency, but this is not observed in other breast cancer subtypes." (PMID 29088785, 2017). "In line with our speculation, we found that miR-23a indeed activated Wnt/β-catenin signaling by targeting CDH1 and promoted the TGF-β1-induced EMT and tumor invasion in breast cancer." (PMID 29050223, 2017). "Finally, quantitation of the methylation levels in MDA-MB-453 cell line confirmed a hypermethylated phenotype at CDH1 and GSTP1 promoters beside a differential methylation pattern at DNMT3B promoter in breast cancer." (PMID 28979331, 2017). "The high expression levels of MYLIP and E-Cadherin (CDH1) could significantly elevate the survival rates for breast cancer patients compared with their low expression groups (p = 0.0196 for MYLIP curve, p = 0.0070 for CDH1 curve)." (PMID 28969074, 2017). "However, quantitation of methylation confirmed a hypermethylated phenotype at CDH1 and GSTP1 promoters as well as a differential methylation pattern at DNMT3B promoter in breast cancer." (PMID 28979331, 2017). "For instance, CDH2 promotes cell motility in breast cancer cells regardless of the expression of CDH1." (PMID 28392805, 2017). "Triple-negative breast cancers have been sub-classified into specific molecular subtypes that include basal-like breast cancers (CK5/6-positive and/or EGFR-positive) and claudin-low breast cancers exhibiting low expression of the CDH1 and claudin 3, 4 and 7 genes." (PMID 26988558, 2016). "Instead, a claudin-low intrinsic subtype of breast cancer has been described as a subset of basal-like breast cancers characterized by low to absent expression of claudin 3 and E-cadherin (CDH1), as well as stem-cell like features." (PMID 26556851, 2015). "Methylation-sensitive high-resolution melting was used to screen promoter methylation in a panel of 13 genes reported as methylated in breast cancer (RASSF1A, TWIST1, APC, WIF1, MGMT, MAL, CDH13, RARβ, BRCA1, CDH1, CDKN2A, TP73, and GSTP1) in 29 tumour pairs (16 ipsilateral and 13 contralateral)." (PMID 26452468, 2015). "RASSF1, CDH1 and HIC1 are frequently silenced due to hypermethylation in breast cancer patients." (PMID 25068292, 2014). "Thus, loss of C/EBPβ-mediated gene activation of Cdkn2b, as well as Cdh1 and Cxadr, shifts the TGF-β response in breast cancer cells from growth inhibition to EMT." (PMID 23955085, 2013). "Of the CDH1 repressor genes, ZEB1 has been found by others to be the more-dominant EMT driver, important in stabilizing and maintaining the mesenchymal phenotype in breast cancer systems." (PMID 24283570, 2013). "In breast cancer, reduced CDH1 expression has been found in 50% of invasive ductal carcinomas, whereas CDH1 expression was almost always absent in infiltrating lobular carcinoma (ILC)." (PMID 19116033, 2008). "We suggest that CDH1 promoter methylation, but not mutational inactivation, is part of an entire programme, resulting in EMT and increased invasiveness in breast cancer." (PMID 16495925, 2006).
breast carcinoma (continued). "Our observation that EMT only occurs in breast cancer cell lines with CDH1 promoter hypermethylation and not with a CDH1 mutational inactivation questions the presumed central role of E-cadherin loss as the initial or primary cause for EMT." (PMID 16495925, 2006). "Furthermore, Ca1Mab-3 and Ca1Mab-5 recognized endogenous CDH1-expressing human luminal-type breast cancer cells, such as MCF-7, but not triple-negative breast cancer cells, like MDA-MB-231." (PMID 41459333, 2026). "Moreover, it would be intriguing to study CDH1 promoter hypermethylation as part of the EMT program, which may be responsible for the more aggressive phenotype of breast cancer, thus enabling metastasis." (PMID 40143970, 2025). "This relates to a prior connection that was made that a lack of CDH1 expression could further the progression of breast cancer." (PMID 40757085, 2025). "For example, among 55 breast cancer cell lines, 34 (62%) cell lines exhibited high levels of CDH1 mRNA, 4 (7%) exhibited medium levels, and 17 (31%) cell lines showed low or no detection of CDH1 mRNA." (PMID 37189027, 2023). "CDH1 aberrations are rare in non-lobular breast cancers (2.3% TCGA IC-NST cases)." (PMID 37973922, 2023). "For example, both tumors were mainly composed of epithelial breast cancer cells (EPCAM+) with a similar distribution of hormone receptors (ERBB2 for HER2, ESR1 for estrogen receptor, and PGR for progesterone receptor) and histology markers (CDH1 for E-cadherin)." (PMID 37301892, 2023). "Since inactivation of the CDH1 gene is an important step in the metastasis-promoting process of epithelial–mesenchymal transition (EMT,), elucidation of the involved mechanisms is of importance for a better understanding of the development and progression of human breast cancer." (PMID 36139537, 2022). "In addition, EMT biomarkers CDH1 and VIM were highly expressed in cancer cells, consistent with previous reports showing that TAM promoted EMT progress of cancers (lung cancer, colorectal cancer, breast cancer and ovarian cancer) by SPP1." (PMID 36148946, 2022). "Furthermore, leptin was reported to stimulate the secretion of TGFβ, which leads to the activation of SMAD family member 2 (Smad2), Smad3, and Smad4 transcription factors, the repression of cadherin 1 (CDH1) coding for E-cadherin, and an increased CSC phenotype in breast cancer cells." (PMID 36010901, 2022). "In this work, we could also compare the transcript levels of CDH1 in breast cancer groups differentiated by the presence or absence of Chr1 and 16 aberrations." (PMID 33808143, 2021). "For example, in breast cancer, the GATA3/G9A/NuRD(MTA3) complex inhibited the expression of Zeb2 by catalyzing H3K9 methylation of ZEB2 promoter, while Snail suppressed the expression of E-cadherin by recruiting histone lysine-specific demethylase 1 (LSD1) to CDH1 promoter." (PMID 33996581, 2021). "In addition, patients with CDH1 methylation presented significantly poor OS as well as lower disease‐free survival (DFS), supporting the significance of CDH1 expression as a predictive biomarker of poor prognosis in breast cancer." (PMID 32301282, 2020). "In addition, there was no alteration in the migration activity, confirming that 5-Aza-CdR had no direct effect on the expression of VIM and CDH1 in breast cancer cells with a low level of SIPA1 expression." (PMID 32193333, 2020). "Promoter hypermethylation is a well-known mechanism of transcriptional repression of tumor suppressor genes in breast cancer, including BRCA1, APC, CDH1, FANCF, among others, and may provide a complementary pathway of molecular carcinogenesis, independent of mutations." (PMID 33227964, 2020). "Interestingly, the knockdown of ERK5 in the breast cancer cell line MDA-MB-231 and other in vitro cancer cell models leads to a upregulation in CDH1, a decrease of the mesenchymal marker SERPINE1 (the plasminogen activator inhibitor), and an associated decrease in cell migration and invasion." (PMID 31200510, 2019).
breast carcinoma (continued). "The accumulation of Cdh1 in the cytoplasm might account for the observed higher Cdh1 protein levels in breast cancer cells compared to nontransformed cells." (PMID 31420536, 2019). "Although the biological functions of GRIK3 in breast cancer have been exposed only slightly, additional research should be conducted into the mechanics of its oncogenic effects, such as how GRIK3 inhibits the expression of CDH1 and is the structure of the GRIK3‐centric protein interaction network." (PMID 30977227, 2019). "Furthermore, the immunohistochemical analysis of individual tumor samples showed that I2 treatment in patients with early breast cancer and in co-adjuvant (FEC/TE + I2) treatment in patients with advanced tumors tended to increase the expression of membrane localized E-cadherin (CDH1)." (PMID 31319484, 2019). "Moreover, the effects of CDH3 are dependent on the expression of CDH1 which is generally low to absent in our canine mammary tumor cell lines with low basal Wnt activity." (PMID 31105876, 2019). "Perhaps consistent with this, breast cancers expressing higher levels of the epithelium-promoting miR-200 family that represses the CDH1-suppressing EMP drivers ZEB1 and ZEB2 have poorer outcomes; however, this appeared to be due to mechanisms additional to E-cadherin regulation." (PMID 28750639, 2017). "However, their phenotypes were not outside of the CDH1 spectrum; one had diffuse gastric cancer and the other had breast cancer with lobular features plus a family history of lobular breast cancer." (PMID 26681312, 2016). "In breast cancer, several critical genes reportedly undergo aberrant hypermethylation, including genes involved in cell cycle regulation (p16, Cyclin D2), cell apoptosis (DAPK), DNA repair (BRCA1), cell adhesion (CDH1) and cell signal transduction (ER and RARβ2)." (PMID 26451736, 2015). "In our study, we detected absence of E-cadherin expression in all five cases of ILCs and in four of them there was concomitant CDH1 promoter hypermethylation, suggesting that epigenetic changes of CDH1 gene occurs in breast cancer, irrespective of the histological type." (PMID 16512896, 2006). "However, Cdh1 depletion did not interfere with the proliferation of breast cancer cells." (PMID 35627188, 2022). "In addition, the pathogenic variant carriers for PTEN, CDH1, and STK11 identified from unselected breast cancer patients in this study did not meet the criteria for the Cowden syndrome, hereditary diffuse gastric cancer syndrome, and Peutz-Jeghers syndrome, respectively." (PMID 34606182, 2021). "Interestingly, these mammary tumors exhibited low expression levels of PRLR as well as other luminal and epithelial differentiation markers such as (Elf5, Muc1), claudins, and cell adhesion markers (Cdh1, Ocln), while showing elevated levels of EMT and BCSC markers." (PMID 33446633, 2021). "However, basal-type breast cancer cell lines can undergo EMT without losing their CDH1 expression." (PMID 31105876, 2019). "However, unlike Cdh1, depletion of Cdc20 failed to induce p-Y419-Src in breast cancer cells." (PMID 31420536, 2019). "Previous studies have showed that CDH1 expression is observed in luminal-type breast cancers, such as MCF-7, but not in basal B-type breast cancers, including MDA-MB-231." (PMID 41459333, 2026). "Together, these results indicated that CLDN4 is a direct GRHL2 target while CDH1, ZEB1, or ZEB2 are unlikely to represent direct GRHL2 target genes in luminal breast cancer cells." (PMID 36691073, 2023). "Among EMT-related genes, direct regulation of CLDN4 is corroborated but several targets identified in other cells (including CDH1 and ZEB1) are ruled out by both ChIP- and Bru-seq as being directly controlled by GRHL2 in luminal breast cancer cells." (PMID 36691073, 2023). "Nonspecific breast cancer is not included in the CDH1 spectrum by the IGCLCC, although in a cohort of 25 female CDH1 carriers who reported breast cancer, 32% had invasive ductal carcinoma." (PMID 37761816, 2023).
breast carcinoma (continued). "To investigate the contribution of RNF8 to cancer progression in different breast cancer subtypes, we determined RNF8, SNAI1, and CDH1 expression levels in TNBC and non-TNBC breast cancer subtypes using the TCGA RNA-seq dataset." (PMID 34357122, 2021). "This analysis identified 30/229 known cancer genes (T200 targeted platform) and 11/40 TCGA breast cancer genes that were differentially expressed relative to the normal breast cells, including KRAS, GATA3, CCND1, CDH1, GNAS, and several others." (PMID 28794488, 2017). "No peaks were found at the ESRP2 and CDH1 gene loci in MCF7 cells, which likely reflected the low expression of ZEB1 in luminal‐type breast cancer cells." (PMID 28618162, 2017). "The ‘Fibroblastic’ cluster includes two subclusters: 1A includes the breast cancer cell lines BT549, HBL100, Hs578T, MDA-MB-231, MDA-MB-231* and MDA-MB-435s, which all show CDH1 promoter methylation and are oestrogen receptor negative (ER−)." (PMID 16495925, 2006). "Together, this data indicates that CDH1, ZEB1, and ZEB2 genes do not represent direct transcriptional targets of GRHL2 in luminal breast cancer and their regulation may occur through post-transcriptional regulation in this cellular context." (PMID 36691073, 2023).
gastric cancer (829 papers, 1992 to 2026). A primary or metastatic malignant neoplasm involving the stomach. "Pathogenic variants in the CDH1 gene are associated with a lifetime risk of gastric cancer by age 80 ranging from 33 to 70%, though substantial variability exists across studies." (PMID 41528496, 2026). "Young individuals with germline CDH1 P/LP variants and gastric cancer warrant specialty care in expert centers, ideally in the context of ongoing clinical research." (PMID 39760880, 2025). "Gastric cancer screening is recommended after a diagnosis of a germline CDH1 P/LP variant because incident gastric cancers, although uncommon, have been detected at initial endoscopy." (PMID 39760880, 2025). "A systematic review recommended the prophylactic total gastrectomy in CDH1 mutation-positive persons with family history of gastric cancer." (PMID 41517275, 2025). "The IGCLC has established protocols that advocate for PTG as the primary intervention for CDH1 mutation carriers, especially given the high risk of developing gastric cancer at a young age." (PMID 40585607, 2025). "Overall, the recommendation for PTG in CDH1 mutation carriers is supported by the high penetrance of gastric cancer, the limitations of current surveillance techniques, and the potential for improved outcomes through early intervention." (PMID 40585607, 2025). "It has been reported that the CDH1–160 C>A polymorphism significantly influences the occurrence, development, and prognosis of various cancers, while its specific role in gastric cancer remains controversial." (PMID 40416864, 2025). "For instance, mutations in the ATM gene have been associated with a moderately increased risk for gastric cancer, although its role is less understood compared to CDH1." (PMID 40585607, 2025). "This underscores the dual role of CDH1 mutations in both hereditary and sporadic gastric cancer contexts." (PMID 40585607, 2025). "Recent studies have highlighted the role of various genetic variants beyond CDH1 in gastric cancer susceptibility." (PMID 40585607, 2025). "The mean age of diagnosis for gastric cancer in CDH1 mutation carriers is approximately 38 years, and the presence of multiple microscopic foci of cancer is common, even in asymptomatic individuals." (PMID 40585607, 2025). "The interplay between genetic predisposition due to CDH1 mutations and environmental factors like H. pylori infection and diet highlights the multifaceted nature of gastric cancer etiology." (PMID 40585607, 2025). "Studies have shown that somatic mutations and epigenetic alterations, such as promoter methylation of CDH1, are prevalent in sporadic cases of gastric cancer, particularly in the diffuse type, where they are associated with poor clinical outcomes." (PMID 40585607, 2025). "The CDH1 gene is located on chromosome 16, and its mutations lead to a loss of cell adhesion, promoting the invasive characteristics of gastric cancer cells." (PMID 40585607, 2025). "Changes in the CDH1 gene, which produces E-Cadherin, cause cell adhesion to be lost in gastric cancer, which increases the tumor’s aggressiveness and potential for metastasis, particularly in hereditary diffuse gastric cancer (HDGC)." (PMID 40563418, 2025). "This dose-dependent effect of CDH1 loss demonstrates the critical role of E-cadherin in maintaining epithelial integrity and preventing metastasis in human gastric cancer." (PMID 40673273, 2025). "The CDH1 gene encodes E-cadherin, a protein that is essential for cell adhesion, and mutations in this gene significantly increase the risk of developing gastric cancer and LBC." (PMID 40585607, 2025). "The interaction between CDH1 mutations and environmental factors, particularly diet and H. pylori infection, plays a significant role in the development of gastric cancer." (PMID 40585607, 2025). "The primary aim of this study was to characterize gastric cancer-specific outcomes among AYA with CDH1 P/LP variants who were managed with PTG or endoscopic surveillance." (PMID 39760880, 2025).